LASP1 (LIM and SH3 protein 1)
Description:
Plays an important role in the regulation of dynamic actin-based, cytoskeletal activities. Agonist-dependent changes in LASP1 phosphorylation may also serve to regulate actin-associated ion transport activities, not only in the parietal cell but also in certain other F-actin-rich secretory epithelial cell types (By similarity).
Synonyms: LASP-1; MLN50
Tractability: Antibody: the Human Protein Atlas places it where antibodies can reach. PROTAC: ubiquitination databases record sites on it; its protein half-life has been measured.
Gene: Protein-coding gene on chromosome 17 (38,869,185 to 38,921,771, forward strand). Ensembl gene ENSG00000002834.
Subcellular location: Cytoplasm, cell cortex; Cytoplasm, cytoskeleton
Subcellular location (Human Protein Atlas): Cytosol; Plasma membrane; Focal adhesion sites; Golgi apparatus
Gene Ontology:
Molecular function: cadherin binding; protein binding; actin filament binding; monoatomic ion transmembrane transporter activity
Biological process: monoatomic ion transport; monoatomic ion transmembrane transport
Cellular component: cytoplasm; focal adhesion; cortical actin cytoskeleton; cell cortex; cytoskeleton; postsynapse
Genetic constraint (gnomAD): Loss-of-function variants: 8 observed, 35.15 expected, observed/expected ratio (o/e) 0.23, 90% interval 0.13 to 0.41. The upper end of that interval is the gene's LOEUF score, 0.41, which puts it in group 1 of 6, group 1 being the genes least tolerant of losing a copy. Missense variants: 240 observed, 371.55 expected, observed/expected ratio (o/e) 0.65, 90% interval 0.58 to 0.72. Synonymous variants: 131 observed, 140.76 expected, observed/expected ratio (o/e) 0.93, 90% interval 0.81 to 1.08.
Homologues: Orthologues: chimpanzee LASP1 (100% identical), macaque LASP1 (98% identical), dog LASP1 (97% identical), rat Lasp1 (97% identical), mouse Lasp1 (96% identical), rabbit LASP1 (95% identical), guinea pig LASP1 (83% identical), tropical clawed frog lasp1 (83% identical), pig LASP1 (67% identical), zebrafish nebl (59% identical), Drosophila melanogaster Lasp (51% identical), Caenorhabditis elegans F42H10.3 (47% identical). Paralogues in human: NEBL (45% identical), NEB (42% identical), NRAP (20% identical), KY (11% identical).
Diseases named in the same sentence as LASP1 in open-access papers:
LASP1 is named in the same sentence as 105 diseases in open-access papers, as found by Europe PMC text mining. Sharing a sentence is not in itself a finding about the gene and the disease. The quoted sentences say what the papers report.
breast carcinoma (58 papers, 2007 to 2025). "The LASP1 gene was initially identified in a cDNA library of metastatic axillary lymph nodes from human breast cancer patients and strongly associated with lymph node metastasis and poor clinical prognosis." (PMID 29531214, 2018). "Copy number gain or amplification of the genomic locus of LASP1 at 17q12 was observed in 20-30% of human breast cancers and identified as a hallmark of high-risk medulloblastoma." (PMID 28404954, 2017). "The gene encoding the LIM and SH3 domain protein (LASP1) was cloned two decades ago from a cDNA library of breast cancer metastases." (PMID 25622104, 2015). "A nuclear accumulation of LASP1 is observed in different cancer entities and is associated with worse patient outcome in breast cancer." (PMID 25622104, 2015). "LASP-1 is differentially up regulated in several breast cancer cell lines with E-cadherin-mutations and subsequent accelerated migration." (PMID 18419822, 2008). "However, upstream mechanisms that cause the dysregulation of LASP1 in breast cancer are poorly defined." (PMID 37303940, 2021). "In a second step we analyzed whether loss of LASP1 is affecting gene expression of proteins involved in invadopodia activity and performed differential gene expression analysis of breast cancer MDA-MB-231-shLASP1 control and knockdown cells." (PMID 27588391, 2016). "LASP1 (LIM and SH3 protein 1) is a scaffolding protein that mediates cell migration, proliferation, and survival in several human breast cancer cell lines." (PMID 38575125, 2024). "LIM and SH3 protein 1 (LASP1) was first identified in metastatic lymph nodes in breast cancer patients." (PMID 38789663, 2024). "LASP1 was initially discovered in a search of a breast cancer metastasis library and then reported to be involved in cell invasion, migration, and metastasis." (PMID 37345118, 2023). "An analysis of LASP1 regulated genes in LASP1-depleted breast cancer and hepatocellular carcinoma, revealed a disproportionality high regulation of AP-1 controlled protein expression, and supported the regulation of AP-1 by LASP1." (PMID 36497077, 2022). "This was further supported by reports showing a reduced MMP1, 3 and 9 expression in MDA-MB-231 breast cancer cells after stable LASP1 knockdown." (PMID 36497077, 2022). "LASP1 was first found in breast cancer, and was confirmed to be related to the progression and metastasis of breast cancer." (PMID 35379225, 2022). "The activation of chemokine receptors in breast cancer shifts the pS146-LASP1 landscape to one that is predominated by pY171 on LASP1." (PMID 36497077, 2022). "The LIM and SH3 protein 1 (LASP1) was first identified in lymph nodes of breast cancer patients in 1995." (PMID 36497077, 2022). "Next to a cytosolic location, LASP1 can undergo nuclear translocation as was first observed in the nucleus of human breast carcinoma cells." (PMID 35507100, 2022). "Nuclear localization of LASP1 was first described in breast cancer and was correlated with tumor progression, metastasis, and a reduced overall survival of the patients." (PMID 36497077, 2022). "As an inspiring observation, the knockdown of miR-134-3p or increase in LASP1 levels restored the aggressive malignant characteristic of breast cancer cells that was weakened by PPP1R14B-AS1 depletion." (PMID 37303940, 2021). "Anti-miR-134-3p decreased miR-134-3p levels, whereas the LASP1 overexpression plasmid, pcDNA3.1-LASP1, increased LASP1 levels in breast cancer cells." (PMID 37303940, 2021). "LIM and SH3 protein 1 (LASP1) were originally identified from the cDNA library of breast cancer patients with axillary lymph node metastasis." (PMID 34862361, 2021). "Mechanistically, PPP1R14B-AS1 operates as a miR-134-3p sponge and relieves regulatory effect of miR-134-3p on LASP1 in breast cancer cells." (PMID 37303940, 2021).
breast carcinoma (continued). "In breast cancer cells, cotransfection with miR-134-3p mimic lowered the activity of LASP1-wt; however, such influences were counteracted after the binding sequences were mutated." (PMID 37303940, 2021). "PPP1R14B-AS1 also increased LIM and SH3 protein 1 (LASP1) levels by imitating miR-134-3p in breast cancer cells." (PMID 37303940, 2021). "In summary, PPP1R14B-AS1 facilitated the oncogenicity of breast cancer cells by controlling the miR-134-3p/LASP1 axis." (PMID 37303940, 2021). "Overall, results showed that PPP1R14B-AS1 acted as a ceRNA for miR-134-3p and consequently increased LASP1 levels in breast cancer cells." (PMID 37303940, 2021). "LIM and SH3 protein 1 (LASP1) has been found overexpressed in the amount of tumors including breast cancer and ovarian cancer." (PMID 34615856, 2021). "The protein interacts with newly-identified pro-metastatic protein LASP1 in breast cancer cells, in a manner which is dependent on LASP1 phosphorylation by C-X-C chemokine receptor type 4." (PMID 33668654, 2021). "To summarize, our study highlights the importance of the interplay among PPP1R14B-AS1, miR-134-3p, and LASP1 in promoting the oncogenicity of breast cancer." (PMID 37303940, 2021). "The contribution of the miR-134-3p/LASP1 axis toward the oncogenic roles of PPP1R14B-AS1 in breast cancer cells was evaluated using rescue experiments." (PMID 37303940, 2021). "Rescue experiments further corroborated that the knockdown of miR-134-3p or an increase in LASP1 restored the aggressive malignant characteristics of breast cancer cells that were weakened by PPP1R14B-AS1 depletion." (PMID 37303940, 2021). "To better understand the LASP1-Ago2 interaction we wanted to identify motility-related protein targets of Ago2 that are upregulated in breast cancer." (PMID 32872485, 2020). "Nuclear LASP1 expression is high in advanced and aggressive stages of breast cancer, and is a predictor of poor patient outcome." (PMID 32825729, 2020). "In breast cancer, LASP1 is partially phosphorylated at S146 by PKA or at Y171 by not otherwise specified phosphotyrosine kinases (PTKs)." (PMID 32075106, 2020). "The LIM and SH3 protein 1 (LASP1) was first identified in human metastatic lymph nodes in breast cancer patients." (PMID 32075106, 2020). "LIM and SH3 Protein 1 (LASP1) is an adaptor protein that is overexpressed in breast cancer, and plays a critical role in tumor cell migration and invasion." (PMID 32872485, 2020). "The expression of the endogenous Let-7a targets modulated by the LASP1 phospho-mutants have important functions in many steps of breast cancer progression and metastasis." (PMID 32872485, 2020). "Before we correlate the expression of Snail1 and A20 in breast cancer cell lines, we performed Kaplan–Meier survival analysis to determine the probability of relapse-free survival when the expression of LASP1 and SNAI1 are high in human TNBC tumors." (PMID 32825729, 2020). "LASP1 is an adaptor protein that has been shown to mediate cell migration, proliferation, and survival in several breast cancer cell lines." (PMID 31106142, 2019). "LASP1 was significantly upregulated in breast cancer tissues and cell lines and identified as a target gene of miR-133a." (PMID 31369641, 2019). "Previous studies showed that LASP1 was upregulated in many malignant tumors including nasopharyngeal carcinoma, breast cancer, glioblastoma and colorectal cancer and contributed to tumor proliferation, invasion and metastasis." (PMID 31395079, 2019). "LIM and SH3 protein 1 (LASP1), a structural scaffolding protein and adhesion adaptor protein, was initially identified in breast cancer and was located at 17q12." (PMID 31395079, 2019). "Nuclear LASP1 localization was confirmed in several breast cancer cell lines where the protein increased at S-phase and peaked at a G2/M phase." (PMID 30298118, 2018).
breast carcinoma (continued). "This is in agreement with a report demonstrating enhanced expression and release of matrix metalloproteinases (MMP) by LASP1 in breast cancer cells with high metastatic potential." (PMID 30298118, 2018). "LASP1 was initially identified from a cDNA library of metastatic axillary lymph nodes in breast cancer, suggesting that it acts as a tumor metastasis-associated protein in cancer." (PMID 29980193, 2018). "In this respect, an increased nuclear translocation of LASP1 into the nucleus inversely correlated with patient survival (i.e., poor prognosis) in breast cancer, prostate cancer, medulloblastoma, and hepatocellular carcinoma." (PMID 30298118, 2018). "High LASP1 expression has been detected in breast cancer, colorectal cancer, pancreatic cancer, and prostate cancer." (PMID 29980193, 2018). "In the present study, we identified LASP1 as a direct target of miR-203a-3p in nasopharyngeal carcinoma, in agreement with previous findings in head and neck cancer, breast cancer, esophageal carcinoma, prostate and lung cancers." (PMID 28982387, 2017). "In previous studies, overexpression of Lasp1 was identified as a prognostic factor of patients’ adverse survival in a number of cancer entities, including breast cancer, colorectal cancer, gastric cancer, hepatocellular cancer, lung cancer, etc." (PMID 29088849, 2017). "The Lim and SH3 domain protein (LASP1) is an actin-binding protein and was initially identified from metastatic axillary lymph nodes of patients with breast cancer." (PMID 28404954, 2017). "For example, LASP-1 is present in focal contacts, and the cytosol, as well as perinuclear and nuclear breast cancer cells." (PMID 28266596, 2017). "LASP1 was initially identified from a cDNA library of metastatic axillary lymph nodes of patients with breast cancer, and is reportedly overexpressed in several types of metastatic cancers including CRC." (PMID 27626692, 2016). "The regulatory effect of LASP1 on MMP expression was also observed in BT-20 breast cancer cells as well as in prostate and bladder cancer cell lines." (PMID 27588391, 2016). "In conclusion, we identified LASP1 as a novel regulator protein of invadopodia in breast cancer cells being involved in extracellular matrix degradation by matrix metalloproteases." (PMID 27588391, 2016). "In analogy to our earlier experiments with macrophages, we analyzed LASP1 influence on matrix degradation by invadopodia in breast cancer cells." (PMID 27588391, 2016). "To validate the microarray data, we performed qRT-PCR assays and Western blots for assessing mRNA levels and protein concentration of the matrix metalloproteases before and after LASP1 knockdown in the breast cancer cell line." (PMID 27588391, 2016). "At that time, online microarray data by Duvall-Noelle showed downregulation of MMP9 after LASP1 knockdown in breast cancer cells." (PMID 27588391, 2016). "Initially, LASP1 was reported to be overexpressed in 8% of human breast carcinomas and expression was correlated to gene amplification based on data from BT-474 breast cancer cell line and primary tumors." (PMID 25622104, 2015). "LIM and SH3 protein 1 (LASP-1) was initially identified from a cDNA library of metastatic axillary lymph nodes of breast cancer patients." (PMID 25760690, 2015). "Our comprehensive analysis of publicly available gene expression microarray data confirmed a high significance (p<0.001) for LASP1 mRNA overexpression in human carcinomas compared to adjacent normal tissues for breast carcinoma, ESCC and OSCC." (PMID 25622104, 2015). "Recently, LASP1 was identified as a fusion partner of the zinc-finger transcription factor TRPS1 in the breast cancer cell line ZR-75-30." (PMID 25622104, 2015). "Note that LASP-1 is known to be upregulated in breast cancer, where it was first identified, and in ovarian cancer that are malignancies promoted by female hormonal components." (PMID 25760690, 2015).
breast carcinoma (continued). "LASP-1 was initially identified from a cDNA library of breast cancer metastases, and the gene was mapped to human chromosome 17q21." (PMID 24955835, 2014). "In analogy, reduced cellular migration upon LASP1 knockdown was observed in medulloblastoma, breast cancer, and colorectal cancer." (PMID 24980827, 2014). "A predominant nuclear localization of LASP1 is observed in several cancer entities and was reported to correlate with worse long-time survival in breast cancer." (PMID 24913448, 2014). "LASP1 was initially identified from a cDNA library of breast cancer metastases and the corresponding protein is overexpressed in more than 50% of all breast cancers." (PMID 24980827, 2014). "LASP-1 has been reported to be overexpressed in several types of cancers and metastatic cancer cell lines, such as breast cancer, ovarian cancer and colorectal cancer." (PMID 24955835, 2014). "In breast cancer cells, phosphorylation of LASP1 by ABL kinase occurs during apoptotic processes and is associated with the loss of LASP1 localization to focal contacts." (PMID 24913448, 2014). "Consistently, in several cancer entities such as breast cancer, bladder cancer, squamous cell carcinoma and now PCa, increased LASP1 protein levels are connected to reduced mir-203 RNA levels and concomitant enhanced cell proliferation and migration." (PMID 24980827, 2014). "Among the genes correlated with the G2/M phase, nucleic LIM and SH3 protein (LASP-1) at the G2/M phase is considered essential for oncogenic activity in patients with breast cancer." (PMID 24386158, 2013). "The LIM and SH3 domain protein 1 (LASP-1) was initially identified from a cDNA library from breast cancer metastases tissue and was mapped to human chromosome 17q21." (PMID 22897902, 2012). "We also detected BIRC5 and LASP1 expression at mRNA level in breast cancer cell lines and MCF-10A cell line." (PMID 22713668, 2012). "In metastatic human breast cancer, ovarian cancer, colorectal cancer, malignant childhood medulloblastoma and hepatocellular carcinoma, overexpression of LASP-1 was demonstrated." (PMID 22897902, 2012). "LASP1 is expressed at low basal levels in all normal human tissues, but is over-expressed in metastatic human breast cancer, ovarian cancer and medulloblastoma." (PMID 22713668, 2012). "Rate of LASP1 amplification was determined in micro-dissected primary breast cancer cells using quantitative RT–PCR." (PMID 20461080, 2010). "LIM and SH3 protein 1 mRNA is expressed ubiquitously at low basal levels in all normal human tissues, but is overexpressed in metastatic human breast cancer and ovarian cancer." (PMID 20461080, 2010). "Cytoplasmic LASP-1 protein expression was detected in 95% of the breast carcinomas; thereof 31% showed an additional nuclear LASP-1 staining." (PMID 20461080, 2010). "Consistently, earlier studies revealed a correlation between LASP-1-expression and tumour size as well as nodal-positivity in human breast carcinoma." (PMID 20461080, 2010). "This current study analysed the prognostic significance of LASP-1 on overall survival (OS) in 177 breast cancer patients and addressed the suggested mechanisms of LASP-1-regulation." (PMID 20461080, 2010). "In fact, LASP-1 primarily localizes to focal contacts, but confocal microscopy and Western blot analysis of cytosolic and nuclear preparations of various breast cancer cell lines also confirmed its nuclear localization." (PMID 18419822, 2008). "In a study, which established a prognostic index for nodal-positive breast cancer, all 20 patients were LASP1 positive only differing in mRNA expression levels." (PMID 18419822, 2008). "In this report, LASP-1 expression was significantly higher in invasive human breast carcinomas compared to fibroadenomas with strong cytoplasmatic staining for LASP-1 in 55.4% of the invasive tumours." (PMID 18419822, 2008). "In summary, our observations suggest an expanded role for LASP-1 in biological breast cancer behavior." (PMID 17956604, 2007).